L1CAM (L1 cell adhesion molecule)
Diseases named in the same sentence as L1CAM in open-access papers (continued):
Sharing a sentence is not in itself a finding about the gene and the disease.
colon carcinoma (25 papers, 2010 to 2025). "A recent mouse model of colon cancer demonstrated that L1CAM is upregulated under a hypoxic microenvironment." (PMID 36142656, 2022). "In conclusion, this work provided new insight on the L1CAM involvement in colon cancer metastasis mediated by glycan-specific interaction with E-selectin." (PMID 33167483, 2020). "In this study, we also demonstrated that the neural cell adhesion molecule L1 (L1CAM) is an E-selectin ligand in colon cancer cells." (PMID 33167483, 2020). "L1-CAM overexpression was first described in colon cancer cell lines with aberrantly activated ß-catenin-T-cell factor (TCF) signaling." (PMID 30657059, 2019). "In vivo experiments have demonstrated that L1CAM significantly increases liver metastases in mice inoculated with LS174T colon cancer cells." (PMID 24660028, 2014). "For example, the Wnt/β-catenin/TCF pathway was found to induce the expression of L1cam in advanced colon cancer." (PMID 23806079, 2013). "LEF/TCF binding sites were detected in the L1CAM promoter and an inducible dominant negative TCF, or an siRNA to β-catenin, suppressed the expression of L1CAM in colon cancer cells." (PMID 22888955, 2012). "Further, a siRNAs-mediated knock-down of β-catenin in colon cancer cell lines suppressed β-catenin levels and concomitantly decreased L1CAM expression." (PMID 20799950, 2010). "The study of the immunoglobulin family of cell adhesion molecules has been an evolving area of interest in cancer because both the presence of these molecules and their distribution throughout the tumors have been shown to be clinically impactful, such as L1CAM in endometrial and colon cancers." (PMID 41301074, 2025). "It has been previously shown that b-catenin indeed plays a role in the regulation of L1CAM expression in colon cancer, and that in pancreatic cells, the upregulation of L1CAM is Slug-dependent and TGFb1-dependent and promotes tumor cell migration and chemoresistance." (PMID 40870967, 2025). "Additionally, L1-CAM expressing colon cancer cells, when injected into the spleen of mice, promote the spread of tumor cells forming liver metastasis." (PMID 30657059, 2019). "Furthermore, when tumor cells, including SKOV3 ovarian and HCT116 colon cancer cells, were treated with an L1CAM monoclonal antibody, cell proliferation was reduced by 40–60%." (PMID 24660028, 2014). "In addition, the upregulation of L1CAM was found to enhance cell invasion in the SW707 human colon cancer cell line." (PMID 24660028, 2014). "In colon cancer, ezrin interacts with L1CAM and regulates NF-κB signaling." (PMID 23357878, 2013). "Intriguingly, L1CAM (product of ADAM activity) facilitates NFkB signaling, promoting cell motility in colon cancer." (PMID 34298782, 2021). "We asked whether the L1CAM assay could be conducted with HCT116, a colon cancer cell line with robust L1CAM expression." (PMID 37943774, 2023). "A similar result was also documented in a recent publication, where L1CAM-mediated colon cancer metastasis required NF-κB signaling but did not rely on induction of the EMT." (PMID 25294816, 2014). "Conversely, L1CAM-mediated metastasis in colon cancer cells was shown to be independent of EMT induction and altered the expression of epithelial and mesenchymal marker proteins." (PMID 24660028, 2014).
L1 syndrome (21 papers, 2013 to 2026). "This phenotype closely resembles that observed in L1 syndrome, caused by pathogenic variants in L1CAM, encoding a neural adhesion molecule." (PMID 41720098, 2026). "In neurons from mice expressing L1CAM with the L1 syndrome causing missense mutation D201N, mitochondrial complex I activity and ATP levels are normal while the mitochondrial membrane potential and ROS levels are higher with respect to wild-type neurons." (PMID 40710351, 2025). "In families suspected of L1 syndrome, the determination of L1CAM gene mutations would give a chance of prenatal diagnosis, ultimately avoiding the congenital disabilities relevant to L1CAM gene mutation." (PMID 34914080, 2022). "L1 syndrome, a complex X-linked neurological disorder, is caused by mutations in the L1 cell adhesion molecule (L1CAM) gene." (PMID 34914080, 2022). "L1 syndrome, a complex X-linked neurological disorder with 1:30,000 incidence in newborn males, is caused by mutations in the L1 cell adhesion molecule (L1CAM) gene." (PMID 34914080, 2022). "We also confirmed that AnkG can interact with all 4 members of the L1 family and found that 2 L1 syndrome-associated mutations in L1CAM interfere with its binding to ankyrins." (PMID 35850303, 2022). "Here, we reported one variant of L1CAM gene in two induced fetuses (abnormal fetuses) suspected of L1 syndrome, which is likely disease-causing." (PMID 34914080, 2022). "More importantly, we found that 2 L1 syndrome associated mutations in L1CAM ABD compromise the binding with AnkG through our structural model and glutathione-S-transferase (GST) pull-down experiments." (PMID 35850303, 2022). "In conclusion, we provided two induced fetuses (abnormal fetuses) suspected of L1 syndrome with L1CAM gene variant (c.1108G > A, p.G370R)." (PMID 34914080, 2022). "Whereas HSAS syndrome leads to neonatal or infant death, L1CAM variants survivors are described as affected by CRASH syndrome." (PMID 29290337, 2018). "The collected data suggest L1CAM variant p.G370R was likely related to L1 syndrome." (PMID 34914080, 2022). "Our results provide evidence that the L1CAM gene missense variant (c.1108G > A, p.G370R) may relate to L1 syndrome." (PMID 34914080, 2022). "According to “The L1CAM Mutation Database”, Ig2 harbors the highest number of known disease-causing mutations, suggesting hindering L1CAM homophilic binding plays the main role in CRASH syndrome etiology." (PMID 35052783, 2022). "To evaluate whether the 2 L1 syndrome-related mutations of L1CAM affect its binding with AnkG, we performed both pull-down and ITC assays to examine their interactions." (PMID 35850303, 2022). "Finally, we found that mutations in L1CAM linked to L1 syndrome decrease or disrupt its interactions with AnkG, suggesting that interference with ankyrin-related complex function can contribute to the pathogenesis of neuronal diseases." (PMID 35850303, 2022). "Finally, our structural and biochemical analysis indicated that L1 syndrome-associated mutations in L1CAM, a member of the L1 immunoglobulin family proteins including Nfasc, L1CAM, NrCAM, and CHL1, compromise binding with ankyrins." (PMID 35850303, 2022). "Our results provided evidence that the L1CAM gene missense variant (c.1108G > A, p.G370R) may relate to L1 syndrome." (PMID 34914080, 2022). "Taken together, our results provided evidence that the L1CAM gene missense variant (c.1108G > A, p.G370R) may relate to L1 syndrome." (PMID 34914080, 2022). "The neural cell adhesion molecule L1CAM has been reported to have functional roles in the developing and adult nervous system, and a knock-out mouse mutation of L1 has been associated with the L1 syndrome." (PMID 32547358, 2020). "Indeed, mutations in the L1CAM gene cause a spectrum of neurological disorders that are collectively known as the L1 syndrome or CRASH syndrome, an acronym for Corpus callosum hypoplasia, Retardation, Adducted thumbs, Spasticity and Hydrocephalus." (PMID 28134764, 2017).
L1 syndrome (continued). "Mutations in the L1CAM gene are associated with L1 syndrome, an X-linked recessive disorder." (PMID 24690944, 2014). "The L1 syndrome, a genetic disease that affects 1/30 000 newborn males, is sustained by numerous missense mutations of L1 cell adhesion molecule (L1CAM), an adhesion surface protein active also in transmembrane signaling, essential for the development and function of neurons." (PMID 22973895, 2013). "NOG-derived peptides and L1CAM ED have comparable potency in triggering neurite outgrowth, but only peptides can also rescue the neuritogenesis in a CRASH syndrome cellular model." (PMID 35052783, 2022). "Earlier studies concluded that defects in L1CAM homophilic binding are likely to contribute to L1 syndrome." (PMID 34914080, 2022). "The variable effects observed with the different L1CAM mutants suggest that this function contributes to the marked heterogeneity of symptoms and severity observed in the patients affected by the L1 syndrome." (PMID 22973895, 2013). "Notably, splicing dysregulation in L1CAM underlies the phenotypic spectrum of L1 syndrome - encompassing X-linked hydrocephalus with aqueductal stenosis (HSAS, OMIM #307000), MASA syndrome (OMIM #303350), SPG1, and corpus callosum agenesis (OMIM #304100)." (PMID 40520226, 2025). "A synthetic peptide reproducing such region could both mimic the neuritogenic capacity of L1CAM and rescue neuritogenesis in a cellular model of the CRASH syndrome, where the full L1CAM ectodomain proved ineffective." (PMID 35052783, 2022). "Given the central role played by L1CAM in brain development, it is not surprising that mutations or polymorphisms of the L1CAM gene lead to severe neurological disorders summarized as CRASH syndrome." (PMID 35052783, 2022).
Parkinson disease (21 papers, 2013 to 2026). A progressive degenerative disorder of the central nervous system characterized by loss of dopamine producing neurons in the substantia nigra and the presence of Lewy bodies in the substantia nigra and locus coeruleus. "The capability of the EVID‐biochip to isolate common EVs and detect neuronal EVs associated with Parkinson's disease in human serum is successfully demonstrated, using the transmembrane protein L1‐cell adhesion molecule (L1CAM) as a target biomarker." (PMID 38898558, 2024). "Moreover, L1CAM is widely used as a target biomarker to detect Parkinson-associated neuronal extracellular vesicles in human serum." (PMID 40194557, 2025). "This setup achieved a sensitivity of 1 pg/mL for L1CAM, successfully distinguishing Parkinson’s patients from controls with an area under the curve (AUC) of 0.973." (PMID 40772226, 2025). "L1 cell adhesion molecule (L1CAM, hereafter abbreviated L1) has been shown to reduce the severe consequences of neurological diseases, such as multiple sclerosis, Parkinson’s, and Alzheimer’s disease, in mouse and zebrafish models." (PMID 38474289, 2024). "We established that α‐synuclein level in L1CAM‐immunocaptured exosomes above 14 pg/mL is a robust biomarker across cohorts that distinguishes Parkinson's disease from MSA (AUC, 0.90 vs 0.98) or 4‐repeat tauopathies (AUC, 0.93 vs 0.94)." (PMID 33826157, 2021). "CNS-derived L1CAM+ EVs are found in circulation, and patients with Parkinson’s disease have significantly elevated levels of α-synuclein in plasma EVs compared to healthy controls." (PMID 34360924, 2021). "As an important readout to monitor and predict disease progression, it was shown that α-syn in plasma L1CAM positive EVs correlates with disease severity as assessed by the Unified Parkinson’s Disease Rating Scale (UPDRS) score." (PMID 33203181, 2020). "A study using a similar immunoprecipitation technique that also targeted L1CAM showed a highly significant increase in alpha-synuclein in L1CAM+ EVs in Parkinson's disease (PD) patients compared to controls, which also correlated with disease severity." (PMID 28588440, 2017). "Given that principal data related to neurodegenerative diseases, such as multiple sclerosis, amyotrophic lateral sclerosis, Parkinson’s disease and Alzheimer’s disease were obtained using L1CAM-positive EVs, efforts to overcome present challenges related to its specificity are required." (PMID 38898538, 2024). "Our findings showed increased expression of L1CAM in our patient, indicating that it could contribute to the parkinsonism pathology due to the propagation of altered α-syn." (PMID 39273702, 2024). "Based on the validation of 76 human serum samples, for the first time, this study discovered that the level of L1CAM/neuronal EV particles in serum could serve as a reliable indicator to distinguish Parkinson's disease from control groups with AUC = 0.973." (PMID 38898558, 2024). "For example, we have recently demonstrated that the composite measurement of α-synuclein and clusterin in serum L1CAM-positive EVs was highly accurate (AUC = 0.98) in differentiating Parkinson’s disease from atypical parkinsonism using 735 samples from four independent cohorts." (PMID 34855021, 2021). "Our aim was to assess by means of further testing and analysis whether α‐synuclein measurements in serum L1CAM‐immunocaptured exosomes can differentiate Parkinson's disease from related movement disorders." (PMID 33826157, 2021). "Future studies should therefore combine L1CAM with complementary markers, such as light neurofilament, synaptophysin, or other neuron‐specific proteins or RNAs, to more accurately determine the cellular origin of EVs in Parkinson's disease and related conditions." (PMID 41532955, 2026).
congenital hydrocephalus (17 papers, 2010 to 2025). Hydrocephalus that is present at birth. "Until now, variants in only 1 chromosome of the X gene, L1CAM, were associated with congenital hydrocephalus." (PMID 40892511, 2025). "The downregulation of L1CAM, a gene extensively studied and phenotyped for its role in X-linked congenital hydrocephalus, is particularly noteworthy." (PMID 39118132, 2024). "In boys with congenital hydrocephalus, severe motor and intellectual disabilities, and epilepsy, L1CAM variants should be suspected." (PMID 37251230, 2023). "A previous report indicated that approximately 5% of children with congenital hydrocephalus was X-chromosomal hydrocephalus caused by L1CAM gene mutations." (PMID 34914080, 2022). "The genes responsible for X-linked human congenital hydrocephalus are L1CAM (L1 protein), located at Xq28, and AP1S2." (PMID 35047005, 2021). "Mutations in the L1CAM gene cause neurological abnormalities of variable severity, including congenital hydrocephalus, agenesis of the corpus callosum, spastic paraplegia, bilaterally adducted thumbs, aphasia, and mental retardation (see OMIM)." (PMID 20860806, 2010). "Therefore, there may be an indirect link between congenital hydrocephalus caused by impaired L1CAM function and Rab protein dysfunction." (PMID 40430021, 2025). "Impaired L1 cell adhesion molecule (L1CAM) function has been found to underlie X-linked L1 syndrome, which encompasses congenital hydrocephalus." (PMID 40430021, 2025). "Furthermore, the potential parallels drawn with congenital hydrocephalus (e.g., L1CAM) provide a new perspective on possible shared molecular pathways." (PMID 39118132, 2024). "Moreover, downregulation of multiple proteins associated with congenital hydrocephalus (e.g., L1CAM, PCDH9, ISLR2, ADAMTSL2, and B4GAT1) points to a possible shared molecular foundation between congenital hydrocephalus and iNPH." (PMID 39118132, 2024). "Moreover, our study identifies the downregulation of specific genes, such as L1CAM, PCDH9, ISLR2, ADAMTSL2, and B4GAT1, which have been previously well characterized as playing an important role in congenital hydrocephalus and aqueductal stenosis." (PMID 39118132, 2024).
gastric cancer (17 papers, 2013 to 2025). A primary or metastatic malignant neoplasm involving the stomach. "Here, we aimed to evaluate the diagnostic potential for serum L1CAM in patients with gastric cancers (GC) and esophagogastric junction adenocarcinoma (EJA)." (PMID 32742486, 2020). "Chen indicated L1CAM overexpressed in gastric cancer and associated with poor prognosis and played an important role in the progression and metastasis of gastric cancer." (PMID 32509846, 2020). "Our study demonstrated that L1cam, overexpressed in gastric cancer and associated with poor prognosis, plays an important role in the progression and metastasis of gastric cancer." (PMID 23806079, 2013). "Expression of L1cam was associated with clinicopathological characteristics and prognosis in gastric cancer patients." (PMID 23806079, 2013). "However, further investigation is needed to explore the underlying molecular mechanism by which L1cam promotes gastric cancer progression and metastasis." (PMID 23806079, 2013). "L1CAM, overexpressed in gastric cancer and known to activate the Akt pathway, is significant in gastric cancer progression and metastasis." (PMID 38424563, 2024). "Along this line, L1CAM knockdown in oral squamous cell carcinoma and gastric cancer cells results in a significant decrease in cell proliferation, while overexpression of L1CAM in gastric cancer promotes cell proliferation." (PMID 34228897, 2022). "L1CAM, L1 cell adhesion molecule, is a transmembrane protein which has been reported to promote tumor progression and metastasis in gastric cancer." (PMID 29215599, 2017). "Previously, we have found that L1cam plays a critical role in the progression of gastric cancer and Paxillin is a prognostic indicator of gastric cancer patients." (PMID 27620004, 2016). "Previously, we have found that L1cam plays an important role in the progression of gastric cancer and Paxillin is a prognostic indicator of gastric cancer patients." (PMID 25869101, 2015). "As TNM stage, lymph node and distant metastasis are used as prognostic factors for gastric cancer, we further analyzed the correlation between L1CAM/EPCAM expression and patient prognosis according to Lauren classification, TNM stage and regional lymph nodes." (PMID 24422715, 2013). "Our study suggests that overexpression of EPCAM and L1CAM is common in gastric cancer, and plays an important role in the progression and metastasis of gastric cancer." (PMID 24422715, 2013). "We analyze the relationship between the expression of EPCAM/L1CAM and the prognosis of patients with gastric cancer according to Lauren classification." (PMID 24422715, 2013). "Given that L1cam can promote gastric cancer cell proliferation, migration and invasion in vitro, we further investigated the in vivo effect of L1cam." (PMID 23806079, 2013). "Kodera detected L1CAM expression in 15 of 72 pT3-stage gastric cancer specimens with L1CAM expression more common in intestinal cancer types." (PMID 24422715, 2013). "L1 cell adhesion molecule (L1CAM) and epithelial cell adhesion molecule (EPCAM) have been implicated in the development and progression of gastric cancer." (PMID 24422715, 2013). "Expression of L1CAM and EPCAM in gastric cancer was significantly associated with lymph node and distant metastasis, and poor prognosis." (PMID 24422715, 2013). "Expression of L1cam was evaluated in gastric cancer tissues and cell lines by immunohistochemistry and Western blot." (PMID 23806079, 2013). "Knockdown of L1cam in gastric cancer cell lines significantly reduced cell proliferation, migration and invasion in vitro and suppressed tumorigenesis and metastasis in an experimental nude mouse model." (PMID 23806079, 2013). "Three hundred and sixteen gastric cancer cases had low expression of both L1CAM and EPCAM; 125 gastric cancer cases had high expression of both L1CAM and EPCAM." (PMID 24422715, 2013).